SPR (sepiapterin reductase)
Diseases named in the same sentence as SPR in open-access papers (continued):
Sharing a sentence is not in itself a finding about the gene and the disease.
Wilms tumor (1 paper, 2024). An embryonal neoplasm characterized by the presence of epithelial, mesenchymal, and blastema components. "The identified prognostic genes, particularly GRAMD1A, SPR, EBAG9, RBM47, and RIDA, offer significant potential as both prognostic biomarkers and therapeutic targets for improving personalized treatment in Wilms tumor patients." (PMID 39659787, 2024).
tumor (10 papers, 2014 to 2024). "Correlative analysis of SPR protein levels with clinicopathological features in 97 HCC patients suggested a significant association between SPR expression and age (p = 0.02), T stage (p = 0.019), tumor node metastasis stage (p = 0.019), and sex (p = 0.029)." (PMID 32312975, 2020). "MBC with sPR-positive and HER-2-negative has the similar biological behavior to triple-negative MBC, such as younger age, higher histological grade, larger tumor burden and predisposition to visceral and brain metastasis." (PMID 36910652, 2023). "As the terminal enzyme in the BH4 biosynthetic pathway, SPR has also been studied in tumour progression." (PMID 32734666, 2020). "Taken together, it is necessary to identify a new mechanism of SPR to provide a potential target for tumor therapy." (PMID 32312975, 2020). "Remarkably, Kaplan‐Meier analysis of 88 human NB tumours indicates that high SPR gene expression is significantly correlated with poor survival prognosis." (PMID 32734666, 2020). "Recently, it is reported that SPR is required for the proliferation of mature T cells in vitro and in vivo and that the inhibition of cancer induced by SPR inhibitors links to the immunosuppressive tumour environment." (PMID 32734666, 2020). "The reduction of sepiapterin reductase can affect another pathway, since its inhibition impairs ornithine decarboxylase activity and decrease polyamines concentration in neuroblastomas, attenuating tumor growth." (PMID 34502450, 2021). "The effects of SPR inhibitors on cancer progression depend on the type of tumor." (PMID 32312975, 2020). "Specifically, GRAMD1A was significantly overexpressed in tumor tissues, while RIDA, RBM47, and SPR showed higher expression levels in normal kidney tissues." (PMID 39659787, 2024). "Taken together, SPR is frequently highly expressed in HCC and plays a potential tumor-promoting role in this cancer." (PMID 32312975, 2020). "This current study is the first report on the cellular effects of SSZ on NB tumor cells, presumably due to the inhibition of SPR as predicted by computational docking of SSZ into SPR." (PMID 26093909, 2015). "Increased sepiapterin reductase protein (SR) was found in breast cancer tissues when compared to the adjacent non-tumorigenic tissue and correlated with tumor aggressiveness." (PMID 34502450, 2021). "Moreover, the average SPR protein level was significantly higher in tumor tissues relative to the corresponding adjacent nontumor liver tissues, indicating that SPR was frequently overexpressed in HCC." (PMID 32312975, 2020). "Moreover, SPR is involved in the progression of HCC through a non-enzymatic mechanism, controlling tumor development via the FoxO3a/Bim signaling pathway." (PMID 39659787, 2024). "In brief, our study characterized the clinical implications, functional significance, and nonenzymatic molecular mechanism of SPR in HCC, which could provide a novel clinical prognostic indicator and therapeutic target for this type of tumor." (PMID 32312975, 2020). "Although this dataset does not contain survival data, the correlations between SPR expression and three important clinical NB parameters are highly significant: age at diagnosis (P = 1.9 · 10−23, MYCN tumor amplification (P = 7.9 · 10−15, and INSS stage (various P values < 0.05)." (PMID 26093909, 2015).
cancer (5 papers, 2020 to 2023). A tumor composed of atypical neoplastic, often pleomorphic cells that invade other tissues. "All of these studies provide potential targets for cancer therapy, although further research illuminating the role of SPR in cancer progression and the mechanism underlying the regulation is needed." (PMID 32734666, 2020). "Furthermore, univariate Cox regression analysis revealed that SPR expression, grade, T stage, recurrence, distant metastasis, and cancer embolus were significantly associated with overall survival." (PMID 32312975, 2020). "Furthermore, sepiapterin reductase exhibits a wide distribution in different tissues and is associated with many diseases, including brain dysfunction, chronic pain, cardiovascular disease and cancer." (PMID 32734666, 2020). "Meanwhile, many compounds have been identified in relation to SPR, which has provided potential therapeutics for brain dysfunction, cardiovascular disease and cancer." (PMID 32734666, 2020). "In addition, the discovery of patients with SPD has provided new insight into the role of SPR in disease and provided potential therapeutic strategies and biomarkers for brain dysfunction, chronic pain, cardiovascular disease and cancer." (PMID 32734666, 2020). "Furthermore, cell and animal experiments showed that sepiapterin reductase depletion inhibited cancer cell proliferation and promoted cancer cell apoptosis." (PMID 32312975, 2020). "In recent years, it has come to light that Sepiapetrin reductase (SPR) and GTP cyclohydrolase I (GCH1) play a crucial role in the metabolic processes of cancer cells." (PMID 36908807, 2022). "Some of these studies link the effects of SPR enzymatic inhibition to increased ROS levels exerting anti-proliferative and pro-apoptotic effects on the cancer cell lines, while others point to non-enzymatic functions of SPR in promoting cancer cell apoptosis." (PMID 37251335, 2023). "Moreover, in vitro assays such as real-time cell analysis, and in vivo functional experiments indicated that SPR depletion significantly inhibited HCC proliferation and promoted cancer cell apoptosis through the mitochondrial pathway." (PMID 32312975, 2020). "Moreover, because of the significant role of SPR’s nonenzymatic activity in cancer progression, nonenzymatic sites and inhibitors should also be further investigated." (PMID 32312975, 2020). "Above data highlighted the nonenzymatic function of SPR in modulating HCC cell proliferation and apoptosis, which is a pivotal determinant of cancer development." (PMID 32312975, 2020).
infection (2 papers, 2020 to 2024). The state of being infected such as from the introduction of a foreign agent such as serum, vaccine, antigenic substance or organism. "Upon infection, the phage SPR tail tube protein is synthesized and binds to the middle domain (MD) and C-terminal domain (CTD) of DSR2." (PMID 38729958, 2024).
cardiovascular disease (1 paper, 2020). "Although the key role of SPR in cardiovascular disease has been proposed, the underlying mechanism remains unclear." (PMID 32734666, 2020). "All NOS isoforms require BH4 as cofactor for catalytic activity, reiterating that SPR might be implicated in cardiovascular disease." (PMID 32734666, 2020).
SPR also shares sentences with these, for which no sentence is quoted: Parkinsonism (4 papers); breast cancer (3); multiple sclerosis (2); neurodegenerative disease (2); schizophrenia (2); autonomic diseases (1); Bradycardia (1); colitis (1); developmental delays (1); DHPR-deficiency (1); epilepsy (1); Fabry disease (1); frontotemporal dementia (1); gout (1); GTPCH deficiency (1); hereditary ataxia (1); Hypoglycemia (1); movement disorder (1); myopia (1); neurodevelopmental disorder (1); Noonan syndrome (1); pellagra (1); pneumonia (1); Rapid-onset dystonia-parkinsonism (1); Segawa syndrome (1).